FOXO3 (forkhead box O3)
Diseases named in the same sentence as FOXO3 in open-access papers (continued):
Sharing a sentence is not in itself a finding about the gene and the disease.
sarcopenia (32 papers, 2017 to 2026). Progressive decline in muscle mass due to aging which results in decreased functional capacity of muscles. "A body of research has indicated that a decline in FOXO3 levels in the muscles of the elderly is associated with an elevated risk of sarcopenia, while the activation of FOXO3 has been demonstrated to counteract the process of muscle aging." (PMID 40869996, 2025). "The objective of this review is to open new therapeutical areas of a Foxo3-targeted treatment in sarcopenia and give an insight into their underlying molecular mechanisms." (PMID 38132107, 2023). "Another study reported that IL-6 mediates sarcopenia in cancer-associated cachexia by activating FOXO3 and atrogin." (PMID 28388585, 2017). "Although previous studies employing FoxO1/3/4 triple-knockout and Atrogin-1-deficient cells have established the critical role of the FoxO3–Atrogin-1/MuRF-1 axis in acute muscle atrophy, its causal relevance in naturally occurring chronic sarcopenia remains undefined." (PMID 41568005, 2025). "Notably, a study on sarcopenia, the physiological age-related loss of muscle mass, identified FOXO3 as an up-regulated gene in muscles from old subjects and another study found increased FOXO1 mRNA in aged muscle." (PMID 29529088, 2018). "Indeed, Foxo3-knockout mice showed increased Nfkb expression, leading to T cell hyperproliferation and associated inflammation in vivo closing the loop of inflammation as a driver in sarcopenia." (PMID 38132107, 2023). "In this study, we investigate the impact of RT combined with VT on the IGF-1/PI3K/AKT/FOXO3 axis in patients with sarcopenia." (PMID 41004429, 2025). "This protocol delineates a structured approach to evaluate the combined effects of RT and VT on the IGF-1/PI3K/AKT/FOXO3 signaling axis in an older population diagnosed with sarcopenia." (PMID 41004429, 2025). "Further research is needed to elucidate how these combined exercises influence key molecular pathways, such as the IGF-1/PI3K/AKT/FOXO3 axis, to enhance therapeutic strategies for sarcopenia." (PMID 41004429, 2025). "The highlight of our study is the identification of six potential diagnostic markers for sarcopenia: BTG2, FOXO3, AQP9, SCN1B, CYCS, and GPC3." (PMID 39777262, 2024). "Six biomarkers—BTG2, FOXO3, AQP9, GPC3, CYCS, and SCN1B—were identified alongside a diagnostic model that offers a novel approach for early diagnosis of sarcopenia." (PMID 39777262, 2024). "BETs were found to coordinate the expression of genes associated with muscle atrophy through direct occupancy of catabolic genes by BRD2 and activation of the IL-6/AMPK/FoxO3 axis, leading to the development of sarcopenia." (PMID 37881635, 2023). "Thus, a lower IGF-1 level can lead to a higher FOXO3 activity via the PI3K/AKT pathway, causing protein degradation and skeletal muscle atrophy, thereby resulting in the onset of sarcopenia in older adults." (PMID 41004429, 2025). "Among the various regulatory genes in the musculoskeletal system, FOXO3 is crucial; therefore, its inhibition might be a potential strategy for treating muscle atrophy and sarcopenia." (PMID 41004429, 2025). "In summary, FOXO3-mediated genetic therapy might enable molecular treatment of sarcopenia, if a potent and muscle-specific form of application can be devised." (PMID 38132107, 2023). "The data so far seem to pitch a Foxo3 knockdown as a new target for sarcopenia treatment." (PMID 38132107, 2023). "Given the presence of AAV therapies in ongoing clinical trials (250 trials in 2021), the demonstrated AAV-mediated FOXO3 treatment might depict a starting point for further studies on the genetic treatment of sarcopenia." (PMID 37681900, 2023). "Moreover, it suggests an imbalanced anabolic/catabolic interaction, linking FOXO3 as a potential molecular target for the clinical treatment of sarcopenia." (PMID 38132107, 2023).
sarcopenia (continued). "Additionally, a role for FOXO3 has been suggested in patients with Duchenne muscular dystrophy, while increased FOXO3 phosphorylation was observed in chronic obstructive pulmonary disease patients with sarcopenia." (PMID 31303978, 2019). "Consequently, the hyperactivation of FoxO3-mediated proteolytic pathways constitutes the key molecular basis for the “enhanced breakdown” component of the disrupted protein turnover characteristic of sarcopenia." (PMID 41568005, 2025). "This suggests that it is not the overall expression, but rather the regulation of FOXO3 that might cause sarcopenia." (PMID 38132107, 2023). "Even though in the context of sarcopenia, FoxO3 only recruits the newly imported β-catenin in nuclei and does not affect β-catenin binding on canonical targets, high dosage of FoxO3 may further compete β-catenin away from canonical Wnt targets and inhibit Wnt signaling." (PMID 29717119, 2018). "Similarly, in sarcopenia, oxidative stress contributes to the activation of FOXO1 and FOXO3, driving the muscle protein ligase pathway and autophagic activity." (PMID 41509286, 2025). "In the sarcopenia dataset, BTG2 (AUC = 0.867), CDKN1A (AUC = 0.892), CEBPB (AUC = 0.942), DDIT4 (AUC = 0.792), FOXO3 (AUC = 0.900), NFKBIA (AUC = 0.892), ZBTB16 (AUC = 0.808) and ZFP36 (AUC = 0.775) demonstrated better diagnostic efficacy in distinguishing sarcopenia patients from healthy controls." (PMID 38962732, 2024). "Not coincidentally, FOXO3 is also a transcription factor that plays an important role in OA and sarcopenia." (PMID 38962732, 2024).
heart failure (31 papers, 2011 to 2026). Inability of the heart to pump blood at an adequate rate to meet tissue metabolic requirements. "We found reduced expression of genes associated with heart failure, including a novel circular RNA circ-Foxo3." (PMID 27713910, 2016). "Antibody-mediated IGFBP7 neutralization reversed IGFBP7-induced suppression of Forkhead box O3 (FOXO3a), thereby restoring DNA repair and reactive oxygen species detoxification signals and attenuated heart failure in mice." (PMID 39045455, 2024). "The role of miR-212 as a crucial regulator of pathological left ventricular hypertrophy in heart failure generated by pressure overload has been demonstrated through its regulation of the FOXO3/calreticulin/nuclear factor of activated T cells (NFAT) pathway." (PMID 38074330, 2023). "FoxO3 controls mitochondrial calcium homeostasis in phenylephrine-stressed adult cardiomyocytes and in a rat model of heart failure with preserved ejection fraction, but the direct role of FoxOs on skeletal muscle calcium signaling is not well studied." (PMID 35185597, 2021). "MicroRNA-212 (miR-212) is a crucial regulator of pathologic LVH via FOXO3-mediated pathways in pressure-overload-induced heart failure." (PMID 31380269, 2019). "MicroRNA-212 (miR-212) has been demonstrated previously to be a crucial regulator of pathologic LVH in pressure-overload-induced heart failure via regulating the forkhead box O3 (FOXO3)/calcineurin/nuclear factor of activated T-cells (NFAT) pathway." (PMID 30718600, 2019). "The miR-212/132 cluster is considered to be a central regulator of the development of pressure-overload-induced LVH and heart failure via the repression of the anti-hypertrophic transcription factor FOXO3 in mice with transverse aortic constriction (TAC)." (PMID 31380269, 2019). "MiR-212 was shown to be a key regulator of the development of LVH and heart failure via the repression of the anti-hypertrophic transcription factor FOXO3 and overactivation of the calcineurin/NFAT signaling during heart failure development." (PMID 31380269, 2019). "Ahmetset al. have shown that miR-212 null mice could prevent the heart failure induced by pressure-overload, and directly target the FoxO3, an anti-hypertrophic and pro-autophagic transcription factor." (PMID 27307080, 2016). "Research has shown that Daidzein can effectively inhibit DOX‐induced heart failure in mice by suppressing fibrosis, cell apoptosis and oxidative stress, and regulating energy metabolism through the SIRT3/FoxO3 pathway." (PMID 40785055, 2025). "MiR-212 has been shown to be a key regulator in the development of LVH and heart failure via the repression of the anti-hypertrophic transcription factor FOXO3 and the overactivation of the calcineurin/NFAT signaling during heart failure development." (PMID 30718600, 2019).
bladder cancer (30 papers, 2014 to 2024). "Resistance to cisplatin, a common chemotherapeutic drug used to treat bladder cancer, has been associated with decreased FOXO3 expression in urothelial cell lines." (PMID 25202904, 2014). "In bladder cancer cells, knockdown of transcriptional factor forkhead box O3a (FOXO3a) conspicuously decreased METTL14 expression." (PMID 35974338, 2022). "In bladder cancer, Foxo3 is decreased in vitro and in vivo and promotes apoptosis through targeting miR-191." (PMID 34555810, 2021). "Consistently, the overexpression of circ-Foxo3 in vivo actually promoted the apoptosis of bladder cancer cell lines." (PMID 33833780, 2021). "After inducing the apoptosis of bladder cancer cells, they found that the expression of circ-Foxo3 was significantly upregulated in relation to apoptotic stress." (PMID 33833780, 2021). "Consistently, circ-Foxo3 suppresses bladder cancer progression through circ-Foxo3/miR-191-5p/mRNA cleaved caspase-3 and circ-Foxo3/miR9-5p/mRNA TGFBR2." (PMID 33833780, 2021). "Whereas, we demonstrated in a bladder cancer cell model, the TP agonist U46619 induced FOXO3 phosphorylation in a time dependent manner and was concurrent with increased activated ERK1/2." (PMID 25202904, 2014). "In conclusion, we have demonstrated a novel mechanism of FOXO3 regulation through phosphorylation and acetylation mediated by the thromboxane A2 signaling pathway in bladder cancer." (PMID 25202904, 2014). "Here, we identified FOXO3 as a downstream target of the TP receptor pathway and examined the negative effects of TP signaling on FOXO3 localization and function in the bladder-cancer derived cell line UMUC3." (PMID 25202904, 2014). "Here, we describe a mechanism of TP mediated modulation of FOXO3 activity and localization by phosphorylation and deacetylation in a bladder cancer cell model." (PMID 25202904, 2014). "Nuclear FOXO3 phosphorylation is correlated with high-grade and recurrent bladder cancer." (PMID 38612866, 2024). "For further discussion, it is reported that the overexpression of Thromboxane-A2 isoform-β receptor (TPβ) plays an important role in the process of human bladder cancer, and TP agonist decreased acetylation of FOXO3 via upregulation of SIRT1 in the bladder cancer cell line UMUC3." (PMID 29147649, 2017). "This suggests that antagonizing the TXA2 pathway could be an ideal therapeutic target in bladder cancer in part through its ability to prevent FOXO3 modulation." (PMID 25202904, 2014). "To select the best cell line for examining the levels of modified FOXO3 protein, we immunoblotted a panel of bladder cancer cell lines for the expression of TPβ and FOXO3 and chose the cell line that expressed the highest levels of both proteins (data not shown)." (PMID 25202904, 2014). "Thus, elucidating the effects of TXA2 signaling on FOXO3 expression, phosphorylation, and subcellular localization could reveal new chemotherapeutic targets for bladder cancer treatment." (PMID 25202904, 2014). "The FOXM1 signaling network and its regulators, including FOXO3, PI3K, and AKT, remains putative drug targets in bladder cancer which requires additional work." (PMID 34885040, 2021). "High expression levels of FOXO3, EGFR, and GPC1 as well as low expressions of VEGFA were closely correlated with poorer survival outcomes of bladder cancer patients." (PMID 33962639, 2021). "In an animal study on bladder cancer-bearing mice, MAG downregulated the expression of transcriptional factor Forkhead box O3 (FoxO3), ubiquitin ligase, MuRF-1 and MAFbx/atrogin-1." (PMID 30103472, 2018). "LAG1 longevity assurance homolog 2 (LASS2) and Polypeptide N-acetylgalactosaminyltransferase 1 (GALNT1) were present in bladder cancer patients, whereas Rho guanine nucleotide exchange factor 39 (ARHGEF39) and Forkhead box protein O3 (FOXO3) were only found in controls." (PMID 30769831, 2019).
pulmonary fibrosis (29 papers, 2013 to 2025). Chronic progressive interstitial lung disorder characterized by the replacement of the lung tissue by connective tissue, leading to progressive dyspnea, respiratory failure, or right heart failure. "The depletion of FOXO3 was consequent for increased promoted susceptibility to bleomycin challenge, accompanied by augmented fibrosis and loss of lung function in idiopathic pulmonary fibrosis." (PMID 33655712, 2021). "Collectively, these in vitro and in vivo data indicate that loss of FoxO3 in lung fibroblasts is critically involved in the progression of pulmonary fibrosis." (PMID 29217661, 2018). "CircSPON1 generated from F-spondin 1 (SPON1) under the influence of forkhead box O3 (FOXO3) is involved in pulmonary fibrosis through the suppression of fibroblast activation by inhibiting the translocation of SMAD-3 into the nucleus." (PMID 38321530, 2024). "To bolster our understanding of Foxo3 and Usp18 in the context of pulmonary fibrosis, we scoured the GEO database." (PMID 38025194, 2023). "It is of note that our investigation into an independent dataset further bolsters the potential involvement of Foxo3 in pulmonary fibrosis." (PMID 38025194, 2023). "In summary, we demonstrated for the first time the transcriptional regulation mechanism of FOXO3 in pulmonary fibrosis." (PMID 37416778, 2023). "This study revealed the mechanism of FOXO3-regulated circSPON1 in the development of pulmonary fibrosis." (PMID 37416778, 2023). "Results showed that FOXO3 expression promoted the circSPON1 level in the body, whereas circSPON1 expression promoted the function of FOXO3 to inhibit pulmonary fibrosis." (PMID 37416778, 2023). "In the BLM-induced pulmonary fibrosis mouse model, mice were treated with FOXO3 and circSPON1 overexpressed plasmids and si-circSPON1 through intraperitoneal injection." (PMID 37416778, 2023). "Our data revealed that circSPON1 mediated the role of FOXO3 in pulmonary fibrosis and the role of circSPON1 in the TGF-β/Smad signaling pathway." (PMID 37416778, 2023). "Forkhead box protein O3 (FOXO3) has good inhibition ability toward fibroblast activation and extracellular matrix, especially for the treatment of idiopathic pulmonary fibrosis." (PMID 37416778, 2023). "Similar results were obtained for the lung and restoration of FOXO3 activity blocked bleomycin-induced fibrosis and reverted the idiopathic pulmonary fibrosis myofibroblast phenotype." (PMID 37932771, 2023). "Taken together, these results indicated that FOXO3 and FOXO3-induced circSPON1 were important in the development of pulmonary fibrosis." (PMID 37416778, 2023). "FOXO3 expression significantly decreases in pulmonary fibrosis, which was also confirmed in this study." (PMID 37416778, 2023). "To define the role of FoxO3 on the fibrotic processes in vivo, we employed the classical and well‐characterized bleomycin‐induced pulmonary fibrosis mouse model." (PMID 29217661, 2018). "Employing UCN‐01 to activate FoxO3 in lung fibrosis, this agent was found to inhibit proliferation of IPF fibroblasts as well as donor fibroblasts that were stimulated by FCS, PDGF‐BB, or IGF‐1." (PMID 29217661, 2018). "In summary, these results indicate that FoxO3 has an important role in attenuating the severity of lung fibrosis induced by bleomycin instillation." (PMID 29217661, 2018). "Although circSPON1 was found to mediate the effect of FOXO3 on pulmonary fibrosis in this study, the specific regulatory mechanism of FOXO3 in the alternative splicing of SPON1 pre-mRNA remains unclear." (PMID 37416778, 2023). "Hence, in the occurrence and development of pulmonary fibrosis, how FOXO3 regulates the formation of circSPON1 and the function of circSPON1 in the nucleus still requires further study, and we will focus on this issue in future studies." (PMID 37416778, 2023).
pulmonary fibrosis (continued). "It has been shown that FoxO3 may attenuate the idiopathic pulmonary fibrosis myofibroblast phenotype in vitro and bleomycin-induced lung fibrosis in vivo, prevent the progression of kidney diseases and promote kidney injury after UUO." (PMID 33251198, 2020). "In the pathogenesis of pulmonary fibrosis, Forkhead box protein O3 (FOXO3) inhibits fibroblast activation and ECM deposition via its interaction with TGF-β1-induced Smad3, thereby attenuating idiopathic pulmonary fibrosis (IPF)." (PMID 40969268, 2025). "Thus, the suppressed Foxo3 expression in the presence of TGF-β may hint at an environment conducive to the progression or exacerbation of lung fibrosis, underscoring the need to further explore the molecular mechanisms and potential therapeutic implications of this interaction." (PMID 38025194, 2023). "To study the regulation of circSPON1 by FOXO3 in vivo and the function of circSPON1 in vivo, we established a BLM-induced pulmonary fibrosis model in mice." (PMID 37416778, 2023). "Partial pharmacological restoration of FoxO3 activity can attenuate the IPF myofibroblast phenotype in vitro and bleomycin‐induced lung fibrosis in vivo, illuminating a potential therapeutic strategy." (PMID 29217661, 2018). "In conclusion, this study underscores the pivotal role of cellular senescence in the pathogenesis of idiopathic pulmonary fibrosis (IPF) and identifies four key CS-DEGs (CDKN2A, VEGFA, SOX2, and FOXO3) as potential biomarkers for diagnosis and targets for therapy." (PMID 40557159, 2025). "Importantly, activating FoxO3 using UCN-01 reversed the IPF myofibroblast phenotype in vitro and mitigated bleomycin-induced lung fibrosis in vivo." (PMID 38025194, 2023). "In summary, our findings showed that ASP could downregulate the expression of DANCR, which in turn represses AUF1-mediated FOXO3 translation to suppress the EMT and pulmonary fibrosis." (PMID 32010478, 2020). "Activation of FoxO3 with UCN‐01, a staurosporine derivative currently investigated in clinical cancer trials, reverted the IPF myofibroblast phenotype in vitro and blocked the bleomycin‐induced lung fibrosis in vivo." (PMID 29217661, 2018). "Reactivation of FoxO3 by UCN‐01 reversed the phenotypic change and reverted pulmonary fibrosis." (PMID 29217661, 2018). "Importantly, a reduced expression, as well as inactivation due to increased phosphorylation of FoxO3, was consistently observed in the human IPF fibroblasts as well as in fibroblasts derived from the bleomycin model of pulmonary fibrosis." (PMID 29217661, 2018). "FOXO3 directly bound to SPON1 and its promoter, promoted the formation of SPON1 circRNA, inhibited the nuclear translocation of Smad3 through interaction with Smad3 and sponge Smad7 as the targeted miRNAs to promote Smad7 expression, and ultimately inhibited the progression of pulmonary fibrosis." (PMID 37416778, 2023). "Therefore, we speculated that FOXO3 may affect the expression and function of SPON1 circRNA in pulmonary fibrosis." (PMID 37416778, 2023). "Article: Lee C-M, He C-H, Park JW, Lee JH, Kamle S, Ma B, Akosman B, Cotez R, Chen E, Zhou Y, Herzog EL, Ryu C, Peng X, Rosas IO, Poli S, Bostwick CF, Choi AM, Elias JA, Lee CG (2019 May 13) Chitinase 1 regulates pulmonary fibrosis by modulating TGF-β/SMAD7 pathway via TGFBRAP1 and FOXO3." (PMID 37037591, 2023). "Importantly, even in these Foxo3−/− mice with aggravated bleomycin‐induced pulmonary fibrosis, UCN‐01 failed to rescue fibrosis." (PMID 29217661, 2018). "Chitinase 1 (CHIT1) plays a role in the pathogenesis of pulmonary fibrosis by modulating canonical and noncanonical TGF-β signaling via interaction with TGFBRAP1 and FOXO3." (PMID 37037591, 2023).